CTLA4 (cytotoxic T-lymphocyte associated protein 4)
Diseases named in the same sentence as CTLA4 in open-access papers (continued):
Sharing a sentence is not in itself a finding about the gene and the disease.
tumor (continued). "Hence, given the imbalance between CD4+ T‐cell subsets, we propose adoptive T‐cell therapy (tumour reactive CD4+ Th‐cell reinfusion), CAR T‐cell therapy and immune checkpoint blockade, such as anti‐CTLA4, to reactivate Th cells and inhibit Treg cells." (PMID 36967539, 2023). "Prior studies have noted that patients responding to anti–PD-1 (with or without anti–CTLA-4) therapy have higher baseline TCR clonality in the tumor microenvironment and harbor large clones that gain more DEGs during therapy than do nonresponding patients." (PMID 36719749, 2023). "In the MC38 mouse model, JK184, anti-PD1 or anti-CTLA4 antibody treatment inhibited tumor growth, but the combination treatment almost achieved complete tumor regression in some mice, and no mice died during the 60-day survival observation." (PMID 36635683, 2023). "Thus, the investigation of the role of ICI in PM reached a turning point by exploring the co-targeting of CTLA-4 and of the PD1/PD-L1 axis, increasing the efficacy of ICI therapy and overcoming the mechanisms of resistance in tumor cells." (PMID 38259475, 2023). "Knockdown of CTLA-4 with shRNA also significantly increased proliferation and anti-tumor activity in first- but not second-generation CAR-T cells." (PMID 37596653, 2023). "Anti-CTLA-4 and anti-PD-1/PD-L1 antibodies demonstrated antitumor efficacy irrespective of PD-L1 expression in tumor cells in three phase III trials." (PMID 37894357, 2023). "We next evaluated the in vivo potency of anti-PD-1 and anti-CTLA-4 mAbs as monotherapies, combination and MEDI8500 in non tumour-bearing humanized mice, using GvHD development as a potential predictor of toxicity and potency of these immunotherapies and combinations." (PMID 36936963, 2023). "MIB2 KO markedly restricted tumor growth and improved survival rate when combined with either PD-L1 or CTLA4 mAb, but no mice survived more than 50 days after tumor inoculation." (PMID 36719382, 2023). "Importantly, this study revealed that animals treated with the dual blockade of PD-L1 and CTLA-4 and CSC-DC vaccine conferred significantly more tumor regression than the CSC-DC vaccine alone." (PMID 36900399, 2023). "Individually, opaganib and anti-CTLA-4 antibody had modest effects on the growth of LLC tumors and mouse survival, whereas the combination of opaganib with anti-CTLA-4 substantially inhibited tumor growth and increased survival (p < 0.001)." (PMID 38069222, 2023). "CTLA-4 antibodies also promote intratumorally regulatory T cell (Treg) depletion via the Fc receptor via antibody-dependent cell-mediated cytotoxicity (ADCC), owing to elevated CTLA-4 expression in tumor-infiltrating Tregs." (PMID 37232823, 2023). "The carefully regulated dual CD28/CTLA-4 mechanisms ensure that the anti-pathogen and anti-tumor immune effects are carried out without autoimmune responses and collateral damage to normal tissues." (PMID 37110545, 2023). "Furthermore, KLRB1 expression levels are significantly correlated with tumor purity, immune infiltration, and immunotherapy-related markers such as PDCD1, CD274, and CTLA4." (PMID 37988189, 2023). "Therefore, our future study will explore the potential relationship between VISTA, PDL1/PD1, and CTLA4 in EOC and its synergistic anti-tumor effect." (PMID 36952478, 2023). "On the other hand, CTLA-4 was first discovered in 1987 (earlier than PD-1), but it was not until 1996 that anti-CTLA-4 antibodies were reported to reduce the rate of tumor growth." (PMID 37759706, 2023). "Immune checkpoint blockade (ICB) of PD-1/PD-L1 and CTLA-4 could reinvigorate cytotoxic CD8+ T cells in the TME and dampen tumor progression in numerous types of cancers." (PMID 36626227, 2023). "These promising preclinical data of co-transfection with antigenic tumor mRNA and IPI mAb may also encourage ICBs of CTLA-4 and/or PD-1 pathways." (PMID 37681880, 2023).
tumor (continued). "In some cases, CTLA-4 effectiveness depended on the specific cell line used in the mouse model rather than on the tumor histological origin, e.g., for colon cancer models (effective with CT26 cells, not effective with MC38 cells)." (PMID 36831435, 2023). "Furthermore, myeloid cells possibly suppress anti-tumor responses by secretion of IL10 and interaction via CD80/CD86 with CTLA-4 on reactive CD8+ T cells." (PMID 36761972, 2023). "Finally, we have determined that neoplastic cell-intrinsic CTLA-4, PCDC1 (PD1), CD274 (PD-L1), and PDCD1LG2 (PD-L2) expression is dynamic and varies depending on BC immunophenotype and tumor-immune cell interactions." (PMID 36901916, 2023). "Combining PD-1 and CTLA-4 blockage led to a 60% pCR rate in dMMR patients, and no patients with a pMMR tumor experienced a pCR." (PMID 36672381, 2023). "The engagement of CTLA-4 with its ligand (CD80/86) may also result in immunosuppression against developing tumor cells, by mediating immune evasion and escape mechanism of tumor cells." (PMID 37038154, 2023). "CD8 Tex with elevated expression of multiple inhibitory receptors (PDCD1, CTLA4, LAG3, TIGIT, HAVCR2) and Tregs with high expression levels of FOXP3, TIGIT, and CTLA4 were enriched in the ESCC TME, which contributed to tumor immune escape and immunotherapy resistance." (PMID 37187751, 2023). "This prompted us to next investigate if the addition of anti-PD-1 ICB or anti-CTLA-4 ICB might attenuate the surgery-mediated suppression in lymphocyte killing of OE33 P and OE33 R tumour cells." (PMID 37359545, 2023). "PD‐1 and CTLA‐4 are negative immune regulatory molecules on T cells that can induce immune escape of tumour cells by inhibiting the immune function of T lymphocytes and promote tumour development." (PMID 37927242, 2023). "PD-L1 expression in tumor cells correlates with the intestinal type, number of CD8+T cells and macrophages in the TME of GC, and IFN-γ expression in tumor cells correlates to the presence of suppressive CTLA-4+/IFNγ+ immune cells in the TME and the lymph node." (PMID 36979688, 2023). "We found that addition of a depleting antibody for CD25+ T cells, GR1 expressing myeloid cells, and Ly6G+ cells significantly inhibited the resistance to anti-PD-1/CTLA-4, but did not produce complete tumor regressions." (PMID 37449205, 2023). "After 8-weeks to allow for reconstitution, mice were implanted with B16 tumor cells and treated with combination anti-PD-1/CTLA-4/Ly6C with or without addition of diphtheria toxin (DT) twice a week to deplete the dendritic cells." (PMID 37449205, 2023). "As suggested by others, the development of biomarkers characterizing the tumor-immune phenotype in high-grade serous ovarian cancer may identify patients with a greater likelihood to respond to PD1/PDL1 and CTLA4 blockade." (PMID 37240071, 2023). "HG TMEs revealed abundant exhausted/pro-tumour immune cells with no consistent increase in expression of PD-1, PD-L1 and CTLA4 checkpoints and angiogenic genes." (PMID 37696903, 2023). "In this work, we examined the relationship between immune cells and tumor immune infiltration, and we found that immune inhibitory receptors such as PDCD1, CTLA4, TIM3, and LAG3 may be important for T cell activation in tumor cells." (PMID 38248311, 2023). "The type of therapy received (anti-PD1 with or without anti-CTLA4 antibodies), the type of tumor, the number of prior lines and the sex of the patients were significantly associated with the risk of developing irAEs." (PMID 37865776, 2023). "Furthermore, T-47D and BT-474 cell lines recovered cell-intrinsic CTLA-4 and PDCD1LG2 (PD-L2) expression after tumor-immune cell interactions, respectively." (PMID 36901916, 2023). "Moreover, we performed Tumor Immune Dysfunction and Exclusion (TIDE) algorithm to predict the sensitivity of response to immune checkpoint blockade, including anti-PD1 and anti-CTLA4." (PMID 38095640, 2023).
tumor (continued). "Longitudinal BLI indicated significant delay of tumor growth in mice receiving combined IL-6 and CTLA-4 blockade as compared with isotype control (p=0.002) or single agent (P = 0.017 versus α–IL-6; P = 0.09 versus α–CTLA-4)." (PMID 36881480, 2023). "Furthermore, combined treatment with anti-CTLA-4 and Lacobacillus acidophilus lysates restored the dysregulated CRC microbiome by reducing the abundance of Proteobacteria that was increased after tumor development." (PMID 38035338, 2023). "The other molecules, including IFN-γ, CXCL, CTLA-4, MTAP, SFR4/CPXM1/COL5A1, TILs, CAFs, exosomes, and peripheral blood indicators, may have suggestive significance for tumor immune microenvironment and prognosis of immunotherapy." (PMID 36860322, 2023). "In tumor-immune interactions, the antitumor outcome is guided by various paired stimulatory and inhibitory receptor families (including PD: PD-L1, CD155: TIGIT, CD80: CTLA4, etc.)." (PMID 37838774, 2023). "The principal obstacle for anti-VISTA antibodies has been on-target/off-tumor binding to myeloid cells in the blood, resulting in high potential for CRS, whereas for targeting CTLA-4, the issue lies in disrupting the balance of Treg function and inducing autoimmune syndromes." (PMID 37753969, 2023). "Additionally, complete response rate was found to be markedly higher in these mice (tbLN: 4/6, ntbLN: 3/9, i.p.: 2/7) indicating that CTLA4 blockade, specifically in the tumor microenvironment (TME), was crucial for sustained tumor inhibition." (PMID 37259163, 2023). "To investigate the immune profiles of c-Scorehi tumors across the 25 TCGA tumor types, we evaluated immunomodulatory genes involved in immune checkpoint blockade response, (CD274 [PD-L1], PDCD1 [PD-1], HAVCR2 [TIM3], LAG3, TIGIT, CTLA4, and FASLG)." (PMID 37558751, 2023). "However, a recent study suggests that CTLA4 and PD1 blockade therapy inhibit tumor growth via CD4+ T cells." (PMID 36969495, 2023). "CTLA-4 is an immune checkpoint molecule of the B7/CD28 family expressed by different subsets of T cells (e.g., regulatory T cells, activated CD4+ T cells, exhausted T cells) in addition to tumor cells." (PMID 36835456, 2023). "However, the exorbitant tumor burden could also exaggerate CTL exhaustion, leading to the overexpression of a series of inhibitory receptors at the cell surface, which include programmed cell death protein 1 (PD-1), and cytotoxic T-lymphocyte associated protein 4 (CTLA-4)." (PMID 37868967, 2023). "Since the majority of cancer patients do not have tumor remission following ICIs, researchers have attempted combination strategies; for example, anti-CTLA-4 agents have been utilized along with anti-PD-1 and PD-L1." (PMID 37047684, 2023). "BsAbs are a viable strategy to overcome this obstacle because the simultaneous co-blockade of two cancer antigens, such as CTLA-4 and PD-1, primarily in the TME by BsAbs may restrict immune responses, particularly to the tumor site." (PMID 37441075, 2023). "In comparison, non-specific CTLA4 blockade was found to elicit weaker anti-tumor effect and exacerbated ICI-induced irAEs, especially interstitial pneumonia." (PMID 37259163, 2023). "A great range of immune checkpoint molecules, such as PD-1, PD-L1, CD73, Lag-3, B7-H3, TIM-3, CTLA-4, TIGIT, and VISTA in the tumor microenvironment (TME) are involved in important mechanisms that prevent effector T cells’ anti-tumor activities." (PMID 37008041, 2023). "The CIAO trial evaluated durvalumab (anti-PD-L1) with or without tremelimumab (anti-CTLA-4) in 28 patients prior to surgery, with 29% showing tumor reduction to 10% of the pretreatment volume and 25% showing downstaging of the tumor." (PMID 36765627, 2023). "Furthermore, anti-CTLA-4 makes FOXP3+CD4+ Tregs alleviate their immunosuppressive activities and contribute to anti-tumor immune response." (PMID 36721212, 2023).
tumor (continued). "The IRGPI-high group has high expression of CTLA-4 and a small number of CD8 + T cells in the tumor microenvironment, which may be an indication for a combination of anti-PD-1/PD-L1 and anti-CTLA-4." (PMID 37322434, 2023). "Finally, to verify the role of RAP2C-AS1 in the tumor immune microenvironment, the relationship between RAP2C-AS1 and immune checkpoint genes (CD274 and CTLA4) was analyzed at the RNA level." (PMID 38071230, 2023). "In addition, we examined the expression levels of PD1, PDL1, CTLA4, TGFB1, TIGIT, IDO1, and LAG3 in 51 tumor samples." (PMID 37928532, 2023). "We hypothesized that the BBB was responsible for the limited efficacy by blocking anti-CTLA-4 and anti-PD-L1 from reaching the GBM tumor." (PMID 36839777, 2023). "We could show that not only tumor infiltrating immune cells, but also HNSCC cells harbor cytoplasmic and nuclear CTLA-4 expression." (PMID 37415208, 2023). "PMLA-based ICIs were distributed in the tumor area but not in other healthy brain sites and inhibiting CTLA-4 and PD-1 in the tumor site." (PMID 37735656, 2023). "At optimal concentration, the spleen index was found to be similar to no tumor control mice but significantly lower than that of mice treated with lower doses of anti-CTLA4." (PMID 37259163, 2023). "Interestingly, several clinical trials have shown that the combination of local tumor treatment with T-VEC and systemic administration of ICIs, such as anti-CTLA-4 and anti-PD-1 mAbs, results in increased antitumor efficacies." (PMID 37190279, 2023). "Combination PD-1/CTLA-4 blockade increased the proliferation and infiltration of CD4+ and CD8+ T-cells more than PD-1 blockade alone, and significantly decreased the percentage of tumor infiltrating exhausted LAG3+ TIM3+ CD8+ T cells compared to either alone." (PMID 37449205, 2023). "In addition, because Treg cells express CTLA-4, the anti-CTLA-4 antibody can regulate Treg cells in the tumor microenvironment and induce iRAEs by abolishing the inhibitory function of Tregs." (PMID 37081866, 2023). "CTLA-4 blockade, i.e., the use of antagonist antibodies preventing CTLA-4 engagement by the natural ligands CD80 (B7.1) and CD86 (B7.2), was soon explored as a therapeutic target in tumor models by Allison." (PMID 36831435, 2023). "The rationale behind administering a priming dose of an CTLA-4 inhibitor followed by a PD-L1 inhibitor is that anti-CTLA-4 drugs can restore cytotoxic T cell activation in lymphoid tissues, which would consequently result in increased CD8+ T cell infiltration at the tumor site." (PMID 38069095, 2023). "Anti‐CTLA‐4 use was not examined in this analysis due to its strong correlation with irAE and treated tumour entity." (PMID 37084178, 2023). "As previously reported, HIF-1α increases the expression of a wide range of immune checkpoints such as CTLA-4 on T cells; LAG3, TIM3, and PD-L1 on tumor cells; and PD-L1 and VISTA on MDSCs, thus resulting in the inhibition of T cell proliferation and T cell-mediated lysis." (PMID 37443821, 2023). "Anti-CTLA4 therapy did not effectively inhibit tumor growth in this setting, allowing the examination of the phenotype of T cells in the tumors and spleens of those mice." (PMID 36068918, 2023). "In addition, we compared significant immune checkpoints between “stiff tumor” and “soft tumor” and observed the expression of CTLA4, CD276 and TNFRSF25 was higher in “stiff tumor”, while the expression of CD47 was higher in “soft tumor”." (PMID 37179366, 2023). "Moreover, CTLA-4 is expressed on both ILC1 and NK cells in mouse tumor models, although ILC1 has higher expression than NK cells within the tumor." (PMID 38567059, 2023). "In the untreated tumor, half of all T cells belonged to the exhausted CD8+ T cell cluster, characterized by expression of residence and checkpoint molecules such as PD-1, TIGIT, CTLA-4, LAG-3, CD69, and CD103." (PMID 37209684, 2023).
tumor (continued). "In both combination cases, the early initiation of CTLA-4 ICI treatment led to the better management of the non-irradiated tumor (plus value of x-axis)." (PMID 37174706, 2023). "Furthermore, continuous antigen stimulation leads to the up-regulation of co-inhibitory signalling molecules such as CTLA-4, PD-1, and LAG-3 on tumour-specific lymphocytes, rendering T cells unresponsive." (PMID 37426674, 2023). "Therefore, blocking the interaction between CTLA-4 and CD80/CD86 molecules on the APCs can activate T cells and enhance tumor immunotherapeutic efficacy." (PMID 36733388, 2022). "Tumor immunotherapy is a hotspot in current and future research, and T cell immunoglobulin mucin 3 (TIM3) is another emerging immune checkpoint molecule after PD-1/PD-L1 and CTLA-4." (PMID 36140350, 2022). "These tumors express antigenic and tumor microenvironment (TME) characteristics that make them potential candidates for therapy with checkpoint inhibitors that aim to reactivate the immune response such as anti-PD-1 and anti-CTLA-4." (PMID 35919497, 2022). "Meanwhile, neither positive nor negative levels of CTLA4 in tumor samples were present, and IPS showed a higher level in the low-risk group." (PMID 35053610, 2022). "For instance, the interaction between CD80/86 and CTLA-4 on human DCs and CD4+ T cells has been shown to trigger the expression of indoleamine 2,3-dioxygenase (IDO) in DCs, an enzyme that suppresses T cell proliferation and induces tumor immunosuppression." (PMID 35269922, 2022). "Studies after studies proved the higher incidence and severity of irAE with CTLA4 inhibitors when used alone or combined with PD-1 or PD-L1 agents such as ipilimumab and nivolumab irrespective of the primary tumor treated." (PMID 35558065, 2022). "Given our focus on regional perfusion of TDLN with anti-CTLA-4, we hypothesized that HAse might enhance lymphatic uptake and nodal targeting of administered anti-CTLA-4 and therefore promote even greater anti-tumor efficacy." (PMID 35621582, 2022). "In patients treated with ipilumumab, it has been reported how anti-CTLA-4 can instigate T cell responses to tumor neoantigens regardless of TMB." (PMID 35327339, 2022). "Further, it is to be noted that treatment with anti-CTLA4 mAb did not change the tumor [Na+] concentration in the respective salt-matched cohorts." (PMID 35741331, 2022). "The profile of tumor infiltrating immune cells was analyzed by FACS and the results revealed that the percentage of immunosuppressive CTLA4+ or PD-1+ on CD8+ T cells and CD4+CD25+Foxp3+ Tregs was significantly reduced in nCHI3L1 Ab treatment group compared to that in the IgG group." (PMID 34987649, 2022). "The reason for targeting these proteins is that CTLA-4 is a negative co-stimulation regulator that activates T cells after recognition of its tumor antigen presented by an antigen-presenting cell (APC)." (PMID 35884392, 2022). "We hypothesized that ALPN-202 was unable to induce CD28 costimulation in this model because of its inability to bind mouse PD-L1 and thus the anti-tumor activity was only due to ALPN-202’s ability to bind and block CTLA-4." (PMID 35379805, 2022). "Other studies have shown that the use of Bifidobacterium can reduce IMC without damaging the anti-tumor function of CTLA-4 inhibitors." (PMID 36189293, 2022). "Our research mainly assessed the heterogeneity of tumor-infiltrating immune cells in OV TME and found that three immune checkpoint genes CD274, CTLA-4, and PDCD1LG2, showed negative correlations with risk scores." (PMID 35137909, 2022). "The frequencies of FoxP3−Helios− T cells and CD4+CTLA-4+ T cells in PBMCs were found to have stronger negative correlations in advanced tumor stages, compared to early stages (r = −0.041, p = 0.903 [early]; r = −0.651, p = 0.003 [advanced])." (PMID 36146549, 2022).